LEP (leptin)
Diseases named in the same sentence as LEP in open-access papers (continued):
Sharing a sentence is not in itself a finding about the gene and the disease.
Obesity (continued). "Leptin levels were determined in 287 pre-pubertal children (mean age 8.09 years), classified as follows: ASD with overweightness/obesity (ASD+/Ob+); ASD without overweightness/obesity (ASD+/Ob−); non-ASD with overweightness/obesity (ASD−/Ob+); non-ASD without overweightness/obesity (ASD−/Ob−)." (PMID 36902307, 2023). "Therefore, our results, clearly suggest the role of saroglitazar in the amelioration of hyperleptinemia and leptin resistance which may be one of the potential mechanisms for alleviation of obesity and has not been revealed earlier in the MSG model of obesity." (PMID 36033946, 2022). "In 3 T3-L1 preadipocytes, demethylation did not increase leptin gene expression, and the diet-induced up-regulation of leptin, Mest/Peg1, and sFRP5 gene expression in white adipose tissue (WAT) during the development of obesity in mice is not mediated directly by changes in DNA methylation." (PMID 33736593, 2021). "Our study showed that with the presence of AG490, leptin could not affect the expression of TLR4 and other inflammatory-related proteins which suggested that leptin may regulate TLR4 expression through the JAK2-STAT3 pathway in obesity-related OA." (PMID 34457118, 2021). "An ip administration of leptin (2 mg/kg body weight) effectively reduced food intake and body weight in both control and Myd88ΔGFAP mice fed a STD diet, indicating that astrocyte-specific Myd88 KO did not affect leptin responsiveness under non-obesity conditions." (PMID 32560726, 2020). "Obesity-driven BRCA1 upregulation is not able to be explained by DNA methylation (EPIC array) or by short-term treatment of chorionic villous explants at 2.5% oxygen with tumor necrosis factor α (TNF-α) (50 mg/mL), leptin (100 mg/mL), interleukin 6 (IL-6) (100 mg/mL), or high glucose (25 nM)." (PMID 31940810, 2020). "In addition, the increased CSF–serum leptin ratios in patients with IIH compared with controls suggest that transfer of leptin over the blood–brain barrier is not impaired in IIH, in contrast to obesity." (PMID 29985799, 2018). "This is supported by our finding that impaired leptin signalling may not contribute to the exacerbated diet-induced obesity and impaired diet-induced BAT thermogenesis in Npffr2−/− mice, as HFD did not impair pSTAT3 activation in response to exogenous leptin in these mice." (PMID 30413707, 2018). "Importantly, the fold changes in insulin and leptin levels in our mouse model are in the same range as those in DIO mouse models of EI of metabolic phenotypes, showing the validity of our approach to alter those hormone levels in the absence of obesity." (PMID 26662513, 2016). "The demonstration that BBS patients exhibit greater circulating leptin levels than weight- and age-matched non-BBS controls, indicative of pronounced leptin resistance, bolster the notion that dysfunctional leptin signaling is a key pathophysiological mechanism of obesity in BBS." (PMID 26926121, 2016). "Leptin resistance develops in obesity because the ARH neurons expressing leptin receptors do not become further activated from baseline in response to exogenous leptin; consequently, increased leptin levels do not increase energy expenditure or decrease food intake." (PMID 24288531, 2013). "Data may therefore be different in individuals with greater levels of obesity and poorly controlled diabetes; however, this was not the focus of the current study and our data clearly suggest that obesity and T2DM per se do not alter diurnal rhythms of plasma leptin concentration." (PMID 22623983, 2012). "Although no clinical studies have directly demonstrated that obesity-related hyperleptinaemia induces corticosteroid insensitivity, both PI3K activation and oxidative stress are recognised contributors, suggesting that leptin may promote corticosteroid insensitivity through these mechanisms." (PMID 41376865, 2025).
Obesity (continued). "However, obesity may promote the development of MDD following the activation of pathophysiological mechanisms (inflammation, insulin/leptin resistance, and hypertension) with a negative impact on the neuroimmune status and the neural circuits controlling mood/emotional states." (PMID 40407628, 2025). "A pilot study showed that baclofen (GABABR agonist) administration reduced body weight and serum leptin levels in obese patients with no significant changes in blood pressure or metabolism of glucose and lipid, which suggests targeting GABABR might be a novel approach for obesity treatment." (PMID 41016636, 2025).
Insulin resistance (2,552 papers, 2001 to 2026). Increased resistance towards insulin, that is, diminished effectiveness of insulin in reducing blood glucose levels. "In contrast, LEP is involved in energy balance and metabolic processes, with its upregulation in PE placental samples potentially linked to insulin resistance and inflammation." (PMID 39967661, 2025). "Among adipocytokines, leptin is associated with insulin resistance via shared signaling pathways—such as JAK2/STAT3, MAPK, and PI3K—with insulin in the placenta." (PMID 40725173, 2025). "Increased LEP levels have been associated with insulin resistance and inflammation, both of which are pertinent in the context of PE." (PMID 39967661, 2025). "Conversely, in postmenopausal women, obesity increases levels of estradiol, leptin, and insulin resistance, thereby raising breast cancer susceptibility." (PMID 40243654, 2025). "Clinical and experimental findings have shown that higher levels of leptin are associated with insulin resistance and increased BMI." (PMID 41463113, 2025). "Reduced sleep duration is associated with increased leptin and visfatin levels, potentially contributing to inflammation and insulin resistance." (PMID 40630101, 2025). "A recent study that showed that deficiency in the ERK1/2 protects leptin-deficient mice from insulin resistance, further confirms the causative of ERK1/2 activation in the insulin resistance." (PMID 40234489, 2025). "MAFLD is a major manifestation of metabolic syndrome and is closely associated with leptin and insulin resistance." (PMID 40337517, 2025). "Elevated serum levels of CHI3L1 are a hallmark of metabolic syndrome, intimately linked to insulin resistance and leptin dysregulation." (PMID 41463897, 2025). "Independent of BMI, women with GDM have increased levels of serum leptin and there is a positive association between serum leptin, serum insulin and insulin resistance, suggesting these factors are linked in GDM." (PMID 40045330, 2025). "This revealed that SH2B1-2/SEZ6L2-1 duplications are associated with reduced trunk fat despite higher insulin resistance, a paradoxical finding suggesting leptin pathway modulation." (PMID 40429924, 2025). "While extreme leptin deficiency, as seen in congenital lipodystrophy, is associated with severe insulin resistance and diabetes, our results suggest that leptin plays a minimal role in the pathogenesis of T2DM among the general population in this region." (PMID 41523554, 2025). "In conclusion, the A allele of the rs7799039 variant in the promoter of LEP is associated with lower levels of leptin, and confers a higher risk of insulin resistance." (PMID 41158627, 2025). "Leptin and adiponectin, which are also secreted by adipocytes, have been associated with the development of insulin resistance." (PMID 39942768, 2025). "Leptin resistance impairs glucose metabolism and cardiovascular function, while reduced adiponectin worsens insulin resistance and inflammation, increasing the risk of diabetic ketoacidosis and acute kidney injury." (PMID 40150467, 2025). "Leptin, increasing insulin resistance and increasing triglyceride lipolysis, causes the development of hyperinsulinemia, thus supporting systemic low-intensity inflammation." (PMID 40361972, 2025). "Lower insulin resistance in rats fed Stevia appears to be the main cause of changes in leptin and ghrelin receptor mRNA levels in this study." (PMID 40087612, 2025). "The adiponectin/leptin ratio is a sensitive indicator for assessing the risk of insulin resistance, and cardiovascular diseases." (PMID 41048434, 2025). "For example, the pro-inflammatory let-7a was associated with insulin resistance and had orexigenic properties associated with increased responsiveness to leptin." (PMID 40217882, 2025). "Leptin is a hormone produced by fat cells to regulate body weight and appetite, and studies have shown that higher leptin levels are associated with insulin resistance and elevation in body mass index (BMI)." (PMID 41463113, 2025).
Insulin resistance (continued). "We found its positive association with BMI, glycated hemoglobin, leptin, insulin, IL-8 and IL-10 levels supporting a galectin-1 interconnection with glucose control, insulin resistance and inflammation." (PMID 40698658, 2025). "Resistance to leptin, particularly in skeletal muscles, has been linked to insulin resistance and the development of nonalcoholic fatty liver disease and MetS in children." (PMID 40310144, 2025). "For example, β-cell damage in db/db mice is mainly caused by defects in the leptin signaling pathway, while human type 2 diabetes is more associated with insulin resistance and inflammation." (PMID 41181709, 2025). "The meta-analysis suggests that the A allele of LEP rs7799039 variant is associated with an increased risk of insulin resistance, potentially through its effect on reducing leptin levels." (PMID 41158627, 2025). "Leptin and adiponectin have opposing effects: Increased leptin is associated with insulin resistance and an increase in proinflammatory cytokines, while increased adiponectin is associated with insulin sensitivity and anti-inflammatory effects." (PMID 40985048, 2025). "Increased leptin levels have been implicated in the metabolic disturbances observed in atypical depression, potentially contributing to greater adiposity and insulin resistance." (PMID 40426696, 2025). "Higher BMI, leptin, and sweet-eating scores were associated with higher insulin resistance, whereas restrained eating was inversely related." (PMID 41356005, 2025). "Specifically, exercise would seem to increase serum adiponectin, an important regulator of insulin sensitivity, and reduce leptin, a pro-inflammatory marker associated with insulin resistance." (PMID 40431370, 2025). "Elevated leptin levels, driven by increased fat mass, are associated with both leptin resistance and insulin resistance." (PMID 40214973, 2025). "Elevated leptin levels have been linked to various metabolic disorders, including insulin resistance, T2DM, and chronic kidney disease." (PMID 40362168, 2025). "Studies have shown that elevated leptin concentrations are associated with insulin resistance and the progression of T2DM." (PMID 39812542, 2025). "Specifically, they showed elevated IL1RN (a marker of systemic inflammation), ANGPTL4 (a key regulator of lipid metabolism), DCBLD2 (associated with insulin resistance), and LEP (a hormone for long-term energy balance)." (PMID 40528258, 2025). "Glucocorticoids can also cause insulin resistance, manifesting as increased insulin secretion; thus, high insulin levels indirectly cause an increase in leptin levels." (PMID 40417460, 2025). "Leptin is primarily produced in adipose tissue and high levels are closely associated with insulin resistance and inflammation." (PMID 40542280, 2025). "As a proinflammatory cytokine with multiple functions, TNF-α is involved in inflammatory activity and DKD-associated insulin resistance, whereas IL-6 and leptin can directly affect renal and endothelial function." (PMID 40936744, 2025). "Pro-inflammatory adipokines, leptin, and resistin are positively associated with body weight, fat mass, insulin resistance, obesity, and type 2 diabetes." (PMID 38612666, 2024). "Further investigation of circulating metabolic factors is warranted as increased circulating leptin is associated with increased glucose concentrations and insulin resistance." (PMID 38665215, 2024). "Associations between LAR and insulin resistance indexes are mainly driven by the effect of plasma leptin, which is also directly associated with increased adiposity." (PMID 38289144, 2024). "The association between LAR and insulin resistance was mainly driven by leptin over adiponectin in the present study, given that we found a weak association between plasma adiponectin and insulin resistance." (PMID 38289144, 2024).
Insulin resistance (continued). "In studies in adult individuals, the serum leptin level is positively associated with metabolic indices including increased weight, insulin resistance, and inflammation." (PMID 39227971, 2024). "Despite the fact that determinations of leptin and adiponectin levels in biological material are valuable, the leptin/adiponectin ratio has a higher diagnostic accuracy as a marker of insulin resistance and metabolic syndrome." (PMID 38612666, 2024). "Associations between LAR and insulin resistance indexes were mainly driven by the effect of plasma leptin, which is also directly associated with increased adiposity." (PMID 38289144, 2024). "Previous reports suggest that acidosis is linked with malnutrition in HD patients through an increase in protein catabolism and a decrease in protein synthesis, causing inflammation and insulin resistance, and also diminishing leptin levels." (PMID 38585612, 2024). "In a multivariate linear regression analysis, leptin levels were shown to be positively associated with insulin resistance in 398 middle-aged and elderly Taiwanese individuals (β = 0.226, p < 0.01)." (PMID 39062126, 2024). "Circulating levels of leptin and adiponectin have been previously associated with insulin resistance." (PMID 38289144, 2024). "In epidemiological studies, high concentrations of blood CRP and leptin were associated with high insulin resistance." (PMID 39199499, 2024). "The obese phenotype observed in ob/ob mice, characterized by leptin deletion, is associated with hyperglycemia and insulin resistance." (PMID 38672227, 2024). "Another contributory factor in gallstone pathogenesis is leptin, often linked to hyperleptinemia in cases of insulin resistance." (PMID 38883189, 2024). "On the one hand, leptin has a positive association with adiposity, insulin resistance, and type 2 diabetes mellitus, while adiponectin has a negative relationship with adiposity and insulin resistance." (PMID 38289144, 2024). "Leptin levels are positively associated with insulin resistance while adiponectin has potent insulin-sensitizing effects and enhances insulin secretion." (PMID 38256626, 2024). "Increased leptin secretion causes adipose hypertrophy, insulin resistance, dyslipidemia, hypertension, and thickness of the common carotid artery." (PMID 38668349, 2024). "On the other hand, adipokines such as leptin and resistin, known for their pro-inflammatory characteristics, have been linked to elevated cardiac lipid deposition, insulin resistance, and fibrosis." (PMID 39538244, 2024). "The results indicate that most associations between LAR and insulin resistance indexes are determined by plasma leptin, which in turn is directly related to adiposity." (PMID 38289144, 2024). "Leptin plays a role in regulating proinflammatory cytokines, which are also associated with insulin resistance and T2DM, including the tumor necrosis factor and IL-6." (PMID 38397015, 2024). "In NAFLD concretely, higher leptin levels are associated with greater triglyceride content in the hepatocytes, inflammation, and insulin resistance." (PMID 37996653, 2024). "And adipocytokines produced by abdominal fat itself, such as leptin and adiponectin, disturb the insulin signaling pathway and cause insulin resistance." (PMID 40777932, 2024). "In fact, impaired adiponectin/leptin levels produced insulin resistance in obese rats, and in adiponectin-deficient transgenic mice, improved insulin sensitivity was observed." (PMID 38731880, 2024). "Serum concentrations of leptin and insulin were determined using the enzyme-linked immunosorbent assay method (ELISA), and insulin resistance was calculated using the homeostatic model assessment for insulin resistance (HOMA-IR)." (PMID 37110228, 2023).